TNF (tumor necrosis factor)
Diseases named in the same sentence as TNF in open-access papers (continued):
Sharing a sentence is not in itself a finding about the gene and the disease.
tumor (continued). "TNFα mRNA expression was reduced among all tumor bearing groups compared to vehicle treated animals (F3, 50 = 13.32, p < 0.001, p < 0.05 in all cases, Tukey’s multiple comparisons)." (PMID 28811490, 2017). "Further study indicated that QRHX inhibited cancer-related inflammation in tumor by decreasing infiltration of TAMs and IL-6 and TNF-α production and meanwhile decreased arginase 1 (Arg-1) expression and increased inducible NO synthase (iNOS) expression." (PMID 28630636, 2017). "For instance, the ARE binding protein TTP can regulate tumor growth through interacting with the 3′-UTRs of tumor necrosis factor (TNF-α), cyclooxygenase 2 (COX-2) and vascular endothelial growth factor (VEGF)." (PMID 28985357, 2017). "Early release of TNF-α and IL-1β pro-inflammatory cytokines and efficient tumor Ags phagocytosis by monocytes also occurs and would favor subsequent Ag processing and presentation." (PMID 29109725, 2017). "This TNF-α-treated model was different from HaCaT cells, because cancer cells within a tumor are usually exposed to TNF-α secreted by infiltrated macrophages or by the tumor cells themselves." (PMID 29029473, 2017). "It is plausible that during tumorigenesis, BM-MSCs are substantially recruited to the tumor microenvironment and are continuously exposed to the local inflammatory factors, such as TNF-α." (PMID 28542126, 2017). "In this context, the interactions of the vagus nerve, TNFα and the tumor microenvironment have to be further explored in future studies." (PMID 28160574, 2017). "It is known that this cytokine is determinant in the tumor microenvironment, promoting proliferation and invasion of tumor cells, TNF-α also positively regulates anti-apoptotic proteins." (PMID 28662728, 2017). "The results clearly showed that suppressed aerobic glycolysis by shikonin inhibited, whereas activated aerobic glycolysis by TNFα enhanced, the release of exosomes by tumour cells." (PMID 28067230, 2017). "The expression of TNFα, interleukin-6 and C-reactive protein were all increased in the livers of tumor-bearing mice, and KD significantly boosted their expression." (PMID 28915665, 2017). "Although initially identified as anti-tumor molecule, TNF is now considered as a pleiotropic cytokine which plays a major role in immune or inflammatory responses." (PMID 28785220, 2017). "This suggests that TNFα affects pyruvate metabolism relatively more in epithelial cells from tumor affected breasts compared to non‐affected breasts." (PMID 28369883, 2017). "In line with this, we demonstrated a significant enhancement of TNF-α secretion in S180 tumor-bearing mice after 8 d treatment with hemocyanin." (PMID 28854214, 2017). "We chose four genes—IL627,28, IL829, TNF30,31, and ICAM132—because promoter analysis of several tumor cell lines showed that they are induced by TNF-α, a representative inducer of NF-κB activation, through NF-κB binding site(s) present in their promoters." (PMID 28924147, 2017). "We have recently shown that MCF-7 (breast) and A2780 (ovarian) tumor cells exhibited increased production of TNF-α, 48 hours after treatment with 3 to 45 nM docetaxel." (PMID 28915246, 2017). "Tumor associated macrophages produce high amounts of cytokines such as interleukin-6 (IL-6), interleukin-8 (IL-8), monocyte chemotactic protein 1 (MCP-1) and tumor necrosis factor alpha (TNFα) to alter the tumor progression in different ways." (PMID 28832545, 2017). "When activated with poly(I:C), TAMs robustly produced TNF-α in 3LL (mouse lung carcinoma cell line) tumor in mice, resulting in tumor cell death and growth suppression." (PMID 29312355, 2017). "What’s more, PDTC inhibited muscle atrophy and lipolysis in cells models in vitro induced by TNFα and C26 tumor medium." (PMID 29311924, 2017). "TNF-α, another Th1 cytokine produced by activated T cells, is able to induce tumor cell necrosis and enhance the activity of NK and T cells." (PMID 29268708, 2017).
tumor (continued). "TRAIL, a TNF (tumor necrosis factor) superfamily member, is considered to be an endogenous anticancer agent because of its selective cytotoxicity against tumor cells compared to normal primary cells." (PMID 28587286, 2017). "In earlier studies on CD95-signaling in type I tumor cells and also in our previous studies on TNF-signaling, we found that ligation of the receptor resulted in their internalization." (PMID 28223543, 2017). "The level of TNF-α in all doses of l-CDL treatment groups was significantly lower than the tumor group and dose-dependent (p < 0.05, p < 0.01)." (PMID 28587280, 2017). "As part of the tumour immunological microenvironment analysis, we determined the relative expression of pro-inflammatory (IL-1β, TNF-α, and IFN-γ), as well as regulatory (IL-10 and TGF-β) cytokines in tumour tissue." (PMID 28874690, 2017). "It was reported that MCP-1 favors tumor angiogenesis and early tumor growth by inducing TNF-alpha, IL-1alpha, and VEGF secreted mainly by tumor-associated macrophages." (PMID 29318162, 2017). "In myeloid cells, activation of NF-κB increases the secretion of proinflammatory cytokines, such as TNF-α and IL-6, which enhance the inflammation and eventually leads to a rapid proliferation of tumor cells." (PMID 28402257, 2017). "Targeting of TNFα to the tumor vasculature has already been shown to upregulate adhesion molecule expression on the surface of endothelial cells and subsequently enhance CD8+ cytotoxic T cell infiltration." (PMID 29312327, 2017). "TNFα production within CT26 tumours was confirmed by ELISA and therapeutic studies indicated that MG-TNFα can impede tumour growth without inducing significant systemic toxicity." (PMID 28662099, 2017). "The treatment of tumor-bearing mice with NGF resulted in a reduction of tumor volume by 72%, increased lymphocytic infiltration of the tumor tissue, elevated levels of serum IL-1β and TNF-α and an increase in the activities of both SDH and LDH in EAC cells." (PMID 28878143, 2017). "TNFα evoked release of tumor-promoting chemokines such as CCL2 (MCP-1), CCL5 (RANTES) and CXCL8 (IL-8) trigger infiltration of CCR2/CCR5 receptor bearing leukocyte sub-populations (LSPs) including TAMs, MDSCs, TANs, Tregs, MAMs and CAFs." (PMID 28441391, 2017). "Upon arriving at the tumor site, they release IL-1β and tumor necrosis factor-α (TNF-α) to achieve anti-tumor effects." (PMID 28753959, 2017). "Due to the important role in the cell cycle, tumor necrosis factor alpha (TNF-α) is considered as a potential tumor treatment strategy." (PMID 28931402, 2017). "Here we used C26 tumor medium or TNFα to induce atrophy of mature C2C12 myotubes and lipolysis of mature 3T3-L1 adipose cells in vitro, which mimics the wasting of skeletal muscle and adipose tissue in vivo." (PMID 29311924, 2017). "To mimic an AFG1-induced tumor-associated inflammatory microenvironment in vitro, we treated A549 cells and human macrophage THP-1 (MΦ-THP-1) cells with AFG1, TNF-α and/or IL-6 respectively." (PMID 28801561, 2017). "In TLR4+/+ tumor-bearing mice, the levels of TNF-α and IL-6 in APS and LPS groups were significantly higher than those in NS and ADM TLR4+/+ groups (P < 0.05)." (PMID 28303957, 2017). "In this CAC model, it has been reported that neutralization of the cytokine TNF-α and the transcription factor NF-κB reduces tumour proliferation." (PMID 28099146, 2017). "It is interesting that patient 14 experienced a significant increase in CRP, IL-6, and TNF-α level, but a significant decrease in tumor marker CEA levels." (PMID 29268708, 2017). "Our recent work suggests that the activation of immune cells in the tumor microenvironment by tumor cells leads to the secretion of soluble factors such as TNF-α by the activated immune cells and induction of the more aggressive EMT phenotype by the tumor." (PMID 27374101, 2017).
tumor (continued). "In fact, TNFα is enriched in the tumor stroma and activation of NF-κB signaling leads to transcription and secretion of inflammatory cytokines and chemokines as mediators of tumor progression." (PMID 28159925, 2017). "TNF-α is known to be a typical pro-inflammatory cytokine that is involved in protection against infection, and for its anti-tumour effect." (PMID 28231775, 2017). "Small-molecule inhibitor of apoptosis (IAP) antagonists, called Smac mimetic compounds (SMCs), sensitize tumours to TNF-α-induced killing while simultaneously blocking TNF-α growth-promoting activities." (PMID 28198370, 2017). "Proinflammatory cytokines (IFNγ, MCP1, MIP1α, and TNFα) and myeloid differentiation factor (Endoglin) were increased in myeloid cells from p65 KO tumor, which demonstrated an influence on CD8+T cell proliferation." (PMID 29062041, 2017). "In preclinical mouse models genetic evidence has been provided that cytokines produced by the pro-inflammatory T helper cell subsets Th1 and Th17, in particular tumor necrosis factor (TNF), IL-6, IL-23 and IL-17, promote tumor growth and survival." (PMID 28881611, 2017). "Using multiplex ELISA, we observed a significant reduction in tumor cytokine levels of TNF (P = 0.002), and IL-6 (P = 0.014) in Losartan-treated compared to control tumors." (PMID 28416734, 2017). "This pre-clinical research suggested anti-TNF-α therapy as an alternative to suppress tumor growth and metastasis in PDAC." (PMID 28282928, 2017). "E. coli MG1655 was employed to deliver and produce the therapeutic biomolecule TNFα inside murine tumours." (PMID 28662099, 2017). "TNF-α has been shown not only to selectively destroy tumor vasculature, but also increase tumor vessel permeability, thus, improving drug penetration into tumors." (PMID 29276511, 2017). "Control tumor cells were grown in parallel with medium alone (Group 1) or with TNFα + TGFβ1 only (Group 2)." (PMID 28553282, 2017). "Combining these anti-tumor approaches eventually led, in 1975, to the term tumor necrosis factor (TNF), currently with over 135,000 PubMed hits, far more than any other cytokine, entering the scientific lexicon." (PMID 28451786, 2017). "NK cells are a central component of the innate immune system, secreting different cytokines like IFNγ, interleukin-10 or TNFα to stimulate other immune cells, and are capable to directly destroy tumor cells." (PMID 28690853, 2017). "TNF-α facilitates tumor cell migration and invasion by inducing the transcriptional upregulation of genes associated with EMT such as Snail, Twist, ZEB1, and ZEB2." (PMID 28725636, 2017). "Early release of TNF-α and IL-1β pro-inflammatory cytokines and efficient tumor Ags phagocytosis by monocytes take place and would probably create a favorable context for Ag processing and presentation." (PMID 29109725, 2017). "TNF-α has various antitumor functions including inducing apoptosis, affecting the tumor vascular system and immune regulation." (PMID 28854214, 2017). "Tumor Necrosis Factor alpha (TNF-α) has been shown to be released by tumor cells in response to docetaxel, and lipopolysaccharides (LPS), the latter through activation of toll-like receptor 4 (TLR4)." (PMID 28915246, 2017). "The serum and tumor tissues of mice were used to determine the serum levels of β2-GM and related cytokines TNF-α, IFN-γ, M-CSF, TGF, and VEGF at the same time." (PMID 28713364, 2017). "Due to the potentiality of inducing NF-κB activation and profound inflammatory responses, the clinical usage of TNFα has been limited though it has profound cytotoxic effects on tumor cells." (PMID 29379440, 2017). "Since TNF was first recognized for its tumor killing properties, ambitions were high in the late 1980s that rTNF would be therapeutically valuable to cancer patients." (PMID 28451786, 2017). "Knockout of TNF-Rp55 (TNF receptor p55) or treatment with TNF-α antagonist etanercept reduced mucosal inflammatory cell infiltration, tumor incidence, and tumor size." (PMID 28852270, 2017).
tumor (continued). "Tumor epithelial cell-derived cytokines, including IL-6 and TNFα, induce CAF activation or desmoplasia, characterised by SMA expression." (PMID 28416734, 2017). "Then, tumor xenograft assays showed that the treatment with TNF-α significantly promoted the growth of MDA-MB-468 cells in nude mice, whereas silencing of HBXIP remarkably attenuated the tumor growth." (PMID 28938560, 2017). "We have significantly observed higher levels of TNF-α in BC, which act in tumor cell survival through activation of the Factor nuclear kappa B (NF-κB) and Signal transducer and activator of transcription 3 (STAT3) signaling pathways." (PMID 29186783, 2017). "Altogether, the host body weight, tumor development, and the TNF-α response were affected similarly by titrated doses of Salmonella and purified LPS." (PMID 28445131, 2017). "In human tumor biopsies maintained in ex vivo culture, EnAd mediated release of pro-inflammatory mediators such as TNF-α, IL-6, and HMGB1." (PMID 28345021, 2017). "In this model, TNF-α as a tumor promoter stimulates TNFR1, followed by NF-κB and/or p38/MAPK signaling leads to the activation of transcriptional factor STAT3, which results in the up-regulation of oncoprotein HBXIP." (PMID 28938560, 2017). "Laminarin also induced the maturation of dendritic cells in tumor-draining lymph nodes and protected interferon-γ and tumor necrosis factor-α and proliferation of OT-I and OT-II T cells in tumors." (PMID 28423736, 2017). "TNF-α is also implicated in promoting invasion and migration of BCa cells through stimulating the secretion of matrix metalloproteinases-9 (MMP-9) in the tumor microenvironment." (PMID 29190997, 2017). "Various mechanisms are described by which NK cells directly kill tumor cells, which include the release of soluble cytotoxic molecules such as perforin or granzyme, or the induction of apoptosis by the Fas–FasL or the TNF pathway." (PMID 29213274, 2017). "During the early stages of tumor development, TAMs seem to acquire a classical activated M1 phenotype secreting proinflammatory mediators, such as IL-1, IL-6, TNFα, IL-23, and iNOS, which are involved in tumor initiation." (PMID 28769537, 2017). "Elevated TNF-α levels observed in ascites with EOC cells suggests an inflammatory process that possibly benefits tumor development." (PMID 28513532, 2017). "Tumor necrosis factor-α (TNFα) is involved in tumor invasion and metastasis by inducing epithelial to mesenchymal transition (EMT)." (PMID 29109804, 2017). "Tumor-associated overexpressions of TGF-β, TGF-α, EGF, VEGF and TNF-α promote GBM cell survival and proliferation." (PMID 28883992, 2017). "Th1 cytokines, including IFN-γ, IL-2, and TNF-α, enhance the cytotoxicity of CIK cells, whereas Th2 cytokines like IL-6 and IL-10 is associated with tumor immune escape." (PMID 28404886, 2017). "Our findings suggest that DMDD inhibits tumor growth and metastasis by reducing the production of inflammatory cytokines, inducing apoptosis of the tumor cells, and blocking the TNF-α/NF-κB/MMPs pathways." (PMID 28751740, 2017). "But several lines of evidence now suggest that TNFα is one of the major mediators of cancer-related inflammation and acts as a crucial tumor-promoting factor." (PMID 29109804, 2017). "The combination of anti-TIM-3 and anti-PD-1 slightly, yet not significantly, attenuated tumor growth as compared to anti-PD-1 alone, whereas combining anti-TNF and anti-PD-1 proved to be more potent at reducing and slowing down tumor growth." (PMID 29273790, 2017). "Inflammatory cytokines such as TNF-α occupy much of the tumor microenvironment, fostering tumor cell proliferation, survival and migration." (PMID 29228633, 2017). "The delivery of TNFα to tumor blood vessels has also been investigated by using a fusion protein composed of mouse TNF-α and a high-affinity antibody fragment targeted to the extradomain B of fibronectin (L19mTNF-α)." (PMID 28067804, 2017).
tumor (continued). "Vδ2+ cells produce significant amounts of pro-inflammatory cytokines like TNFα and IFNγ in order to counteract bacterial infections or tumour development." (PMID 28076364, 2017). "In particular, NGR and Cysteine-asparagine–glycine–arginine-cysteine (CNGRC), which was derived from NGR peptide, have been proven to be useful for delivering cytotoxic drugs, proapoptotic peptides, and tumor necrosis factor-α (TNF) to tumor vasculature." (PMID 28489574, 2017). "Nevertheless, not only do the mechanisms decrease the propensity to undergo cancer transformation but also, the mechanisms that increase a tendency towards tumour transformation are intensified by TNF-α." (PMID 29089667, 2017). "The C26 tumor model is well established and characterized by a profound increase of pro-inflammatory cytokines such as IL-6 and TNF-α, severe body weight loss and only a moderate decrease in food intake compared to other CACS tumor models." (PMID 28475119, 2017). "In this regards, the combined action of IFNγ and TNFα has been demonstrated to destroy tumour cells and their stroma thereby essentially contributing to the eradication of established mouse tumours." (PMID 28561041, 2017). "This typically leads to an antiviral state in surrounding cells, but can also result in killing of uninfected tumor cells by cytokines such as tumor necrosis factor α (TNFα)." (PMID 28832539, 2017). "Recent studies showed that changes in cytokine signaling networks, such as transforming growth factor (TGF-β), tumor necrosis factor (TNF), and interleukin (IL), contribute to tumor progression CRC." (PMID 28009989, 2017). "RT further affects the tumor microenvironment by inducing increased expression of pro-inflammatory cytokines, such as TNF-α, IFN-γ, IL-1β, IL-6 and IL-12, type-I interferons and chemokines, which stimulate infiltration of immune cells into the tumor." (PMID 28233730, 2017). "Depending on tumor microenvironment and growth phase, neutrophils exert protumoral or antitumoral actions through the production of cytokines (tumor necrosis factor, interleukin-1, and -6) and chemokines, among others." (PMID 28086222, 2017). "The overexpression of Par-4 sensitizes cancer cell lines and tumor cells to cytotoxicity triggered by anticancer drugs such as doxorubicin, 5-Fluorouracil (5-FU) and by stimuli including TNF-α, TNF-related apoptosis-inducing ligand (TRAIL)." (PMID 29278364, 2017). "Using a 3D spheroid-based detachment assay, we found that MCF-7 cells treated by CM of TNFα + TGFβ1-stimulated MSCs (Group 4) had very high capabilities of scattering out of the 3D tumor spheroids." (PMID 28553282, 2017). "In mice, 4-1BB stimulation leads to enhanced NK cell effector mechanisms, but in humans 4-1BB signaling inhibits NK effector activity and reverse signaling through 4-1BBL on tumor cells can induce IL-10 and TNF-α." (PMID 28515726, 2017). "M1 macrophages express high levels of pro-inflammatory cytokines (TNF-α, IL-6, and IL-12) and are capable of killing pathogens and priming anti-tumor immune responses." (PMID 29245934, 2017). "M2b cells are induced by immune complexes, lipopolysaccharides, IL-1R and TLRs ligands; they produce cytokines such as IL-1, IL-6, TNF-α, and IL-10, acting in the metastasis control, suppressing tumor growth and inducing a Th1 response." (PMID 28970834, 2017). "TNFα, mainly derived from activated macrophages, is a well-known cytokine that regulates the inflammatory processes in tumor development." (PMID 28945218, 2017). "Indications supporting this possibility include an early TNF-α response, required to disrupt tumor vessels, and a window of opportunity where bacteria escape the primary tumor and circulate within the first hours of infection." (PMID 28637010, 2017). "CD8+ T cells are cytotoxic and kill target tumor cells or promote tumor destruction via secretion of effector cytokines such as interferon-c or tumor necrosis factor." (PMID 28977947, 2017).